STAT1 (signal transducer and activator of transcription 1)
Diseases named in the same sentence as STAT1 in open-access papers (continued):
Sharing a sentence is not in itself a finding about the gene and the disease.
chronic GVHD (2 papers, 2016 to 2023). "In chronic GVHD patients, STAT1 activation by type-I IFN seems to be critical in oral mucosal inflammation." (PMID 27148267, 2016). "Recently, a report showed that SOCS1 expression was abolished in acute or chronic GVHD patients, suggesting that IL-22-induced STAT1 is no longer inhibited in this context." (PMID 27148267, 2016). "Indeed, a higher level of activated STAT1 in keratinocytes has been reported in severe chronic GVHD patients as compared with those patients with no oral lesions." (PMID 27148267, 2016).
chronic hepatitis C (2 papers, 2010 to 2011). "The present study is the first report concerning IL28B and STAT1-nuclear translocation in hepatocytes being independent predictors of response to treatment with peginterferon and ribavirin in chronic hepatitis C patients." (PMID 22174846, 2011). "It was also revealed that IL28B and STAT1-nuclear translocation in hepatocytes are independent predictors of response to treatment with peginterferon and ribavirin in chronic hepatitis C patients." (PMID 22174846, 2011).
coagulopathies (2 papers, 2014 to 2023). "Suppression of STAT1 pathway leads to compensatory STAT3 hyper-activation, which is associated with elevating plasminogen activator inhibitor-1 (PAI-1), and consequently leads to affliction with coagulopathies." (PMID 36656874, 2023). "Functional SNPs in these genes and their action may be exaggerated by coagulopathies (ACE, AGT) or by apoptosis (STAT1)." (PMID 25264875, 2014).
colorectal adenocarcinoma (2 papers, 2022 to 2025). The most common type of colorectal carcinoma. "For the two transcription genes highly expressed in CSCC, TP63 could be used as a poor prognostic marker of colorectal adenocarcinoma, however, the oncogene function of STAT1 in colorectal adenocarcinoma was controversial." (PMID 35194959, 2022).
cyst (2 papers, 2016 to 2022). A sac-like closed membranous structure that may be empty or contain fluid or amorphous material. "One unanticipated observation was that the loss of STAT1 in astrocytes resulted in altered cellular distribution of the cyst stage." (PMID 27834206, 2016). "Together, these results reveal that STAT1 signaling in astrocytes is essential for the local control of parasite replication and suggest that STAT1 mediates astrocyte resistance to cyst formation." (PMID 27834206, 2016). "Together, these observations suggest that the activation of STAT1 in astrocytes inhibits cyst formation." (PMID 27834206, 2016). "Alternatively, there are host cell pathways, such as signaling through CD73, which promote cyst formation, and STAT1 signaling in astrocytes may disrupt these events." (PMID 27834206, 2016). "Knowing that STAT1 is important in astrocyte immune functions under normal circumstances should provide novel leads for therapeutic strategies to eradicate the cyst stage and better manage TE without compromising the neuroprotective effects of these glia." (PMID 27834206, 2016).
cysticercosis (2 papers, 2021 to 2024). "The purpose of this study was to evaluate the role of STAT1-mediated signaling in determining the outcome of experimental murine cysticercosis by the cestode T. crassiceps." (PMID 34684235, 2021). "Our data demonstrate that the STAT1 signaling pathway has a critical role in recruiting inflammatory monocytes that become M2 macrophages and favors experimental cysticercosis." (PMID 34684235, 2021).
dysplasia (2 papers, 2011 to 2022). A usually neoplastic transformation of the cell, associated with altered architectural tissue patterns. "Despite the reduction in the immunosuppressive PD-1/PD-L1 axis and MDSC populations observed in carcinogen induced Stat1-deficient mice, they still displayed significantly higher mortality and burden of dysplasia and neoplasia compared to Stat1 competent mice." (PMID 35595823, 2022).
Encephalopathy (2 papers, 2022 to 2023). Encephalopathy is a term that means brain disease, damage, or malfunction. "A recent study demonstrated that STAT1 signaling plays an important role in hydrocephalus in John Cunningham polyomavirus (JCPyV) encephalopathy." (PMID 36052359, 2022).
Failure to thrive (2 papers, 2021 to 2022). Failure to thrive (FTT) refers to a child whose physical growth is substantially below the norm. "Overall, patients with STAT1 GOF (c.Y289C) mutations showed lower mortality and lower probability of failure to thrive (approximately 13.3% and 15.4% for STAT1 GOF, respectively)." (PMID 36225936, 2022).
Fanconi anemia (2 papers, 2019 to 2021). Fanconi anemia (FA) is a hereditary DNA repair disorder characterized by progressive pancytopenia with bone marrow failure, variable congenital malformations and predisposition to develop hematological or solid tumors. "A previous report of cycloheximide and STAT1 levels in lymphoblastoid cell lines found significant STAT1 degradation within 3 h of cycloheximide treatment, while in cells carrying a Fanconi anemia gene, STAT1 protein levels stayed stable for 17 h after cycloheximide treatment." (PMID 31354696, 2019).
Flavivirus Infections (2 papers, 2023 to 2024). Infections with viruses of the genus FLAVIVIRUS, family FLAVIVIRIDAE. "Taken together, these results indicate that flavivirus infection induces the production of the 81 kDa STAT1, which is probably a cleaved STAT1 species." (PMID 38018976, 2024). "The immunocompromised STAT1-knockout mouse has emerged as an ideal model for studying ZIKV pathogenesis, as it is highly susceptible to Flavivirus infection and lacks active interferon signaling." (PMID 36803804, 2023).
gout (2 papers, 2025). A condition characterized by painful swelling of the joints, which is caused by deposition of urate crystals. "The expression levels of IL-1β, IL-6, JAK2, and STAT1/3 mRNA were significantly lower in the gout group compared to the HC group (all P < 0.001)." (PMID 40170729, 2025). "In GA patients, mRNA expression of IL-6, JAK2, STAT1/3, and IL-1β was notably lower in the gout group compared to the healthy control (HC) group." (PMID 40170729, 2025). "Literature reviews, coupled with network pharmacology and bioinformatics predictions, have identified IL-6 and STAT1/3 as critical targets for anti-gout treatment." (PMID 40170729, 2025). "The STAT family (STAT1/STAT3/STAT4) mediates cytokine signaling in gout pathogenesis." (PMID 40613560, 2025). "Moreover, IL-6, JAK2, STAT1/3, p-JAK2, p-STAT1/3, and IL-1β proteins were markedly higher in the acute gout (AG) group compared to the intercritical gout (IG) and HC groups." (PMID 40170729, 2025). "In the 2h human blood in vitro gout inflammation model, expressions of IL-1β, IL-6, JAK2 mRNA, and IL-1β, IL-6, JAK2, STAT1/3, p-JAK2, p-STAT1/3 proteins were significantly higher compared to both the blank control and PBS-negative control groups." (PMID 40170729, 2025). "In the 6-h acute gout cell model, expression levels of IL-1β, IL-6, JAK2, STAT1/3 mRNA, and their respective proteins—including phosphorylated JAK2 and STAT1/3—were significantly elevated in the model group compared to the blank control group." (PMID 40170729, 2025). "In animal models, targeting IL-6 disrupted the IL6-JAK2/STAT1/3-IL6 feedback loop, offering a potential therapeutic approach for effectively treating gout." (PMID 40170729, 2025). "Furthermore, Compared to 12-hour gout model WT mice, IL-1β, IL-6, JAK2, STAT1/3 mRNA, protein expression, and phosphorylated protein levels were notably decreased in IL-6 KO mice." (PMID 40170729, 2025). "Furthermore, the 2-h human blood ex vivo gout inflammation model showed significantly elevated levels of IL-1β, IL-6, JAK2 mRNA, and their respective proteins, including phosphorylated JAK2 and STAT1/3, compared to both control groups." (PMID 40170729, 2025). "STAT1 and STAT4 may also contribute to immune cell activation in gout pathology." (PMID 40613560, 2025).
idiopathic pulmonary fibrosis (2 papers, 2020 to 2022). Idiopathic pulmonary fibrosis (IPF) is a nonneoplastic pulmonary disease that is characterized by the formation of scar tissue within the lungs in the absence of any known cause. "TS IIA and AS IV and TS IIA and Puerarin were presented here for their excellent performance in protecting against lumbar intervertebral disc degeneration and idiopathic pulmonary fibrosis (IPF) through restricting STAT1 cascade via combined utilization." (PMID 36324680, 2022).
IgA Nephropathy (2 papers, 2016 to 2024). "Four SNPs (rs6718902, rs10199181, rs2066802, and rs1547550) in the STAT1 gene were observed to be associated with MS in Italy and IgA nephropathy (IgAN) in Korea." (PMID 27965977, 2016).
ileitis (2 papers, 2019 to 2021). "Nevertheless, the ability to modulate nitrate levels, either through sustained AG treatment or depletion of STAT1 in myeloid cells and thereby influence microbiome composition during an infection-induced ileitis, highlights potential avenues for precision editing of the enteric microbiome." (PMID 31138751, 2019). "Here, we uncovered the fact that STAT1 was not able to fully restore Paneth cell viability in vivo, suggesting that further factors, triggering cell death, or additional pathways are present in the context of CD manifestations like ileitis." (PMID 34141714, 2021).
invasive carcinoma (2 papers, 2012 to 2017). A carcinoma that is not confined to the epithelium, and has spread to the surrounding stroma. "The cells in Stat1-null invasive carcinomas (tumors) shared these immunophenotypic characteristics." (PMID 28865492, 2017).
IPEX syndrome (2 papers, 2022 to 2025). "Endocrine autoimmunity, while a cardinal feature of APECED and IPEX syndrome, emerged as a prominent feature in patients with STAT1 gain-of-function mutations." (PMID 41394846, 2025). "Of these patients, three had SCID (1 Artemis, 2-RAG1), four had CVID, three had AIRE, one had DOCK8 deficiency, one had IPEX syndrome, one had CGD, one had STAT1, and one had PIK3CD." (PMID 36211419, 2022).
ischemia reperfusion injury (2 papers, 2020 to 2023). Adverse functional, metabolic, or structural changes in ischemic tissues resulting from the restoration of blood flow to the tissue (reperfusion), including swelling; hemorrhage; necrosis; and damage from free radicals. "In vitro, IFN-γ gene expression as well as amplification of downstream STAT1 and inducible nitric oxide synthase (iNOS; a hallmark of ischemia reperfusion injury) was remarkably increased after CS + rewarming." (PMID 36982554, 2023).
kidney cancer (2 papers, 2021 to 2024). Primary or metastatic malignant neoplasm involving the kidney. "We found that five aging-related genes (DUSP22, MAPK14, MAPKAPK3, STAT1, and VCP) from kidney cancer patients were significantly related to patient survival." (PMID 34207247, 2021).
large granular lymphocyte leukemia (2 papers, 2018 to 2020). "All patients exhibit constitutive STAT1 and STAT3 phosphorylation, and the occurrence of STAT5B and STAT3 somatic activating mutations are a hallmark of LGL leukemia." (PMID 31947841, 2020). "Here we further characterize the IFN-γ-STAT1 signaling pathway from IFN-γ-induced activation events through the regulation of IFN-γ production in TL-1 cells, a cell line model of T cell large granular lymphocyte leukemia." (PMID 29474442, 2018). "Dysregulated STAT1, STAT3, and STAT5 signaling is well documented in LGL leukemia." (PMID 31947841, 2020).
lichen planus (2 papers, 2022 to 2025). A chronic, recurrent, pruritic inflammatory disorder of unknown etiology that affects the skin and mucus membranes. "Pathogenesis of Lichen Planus (LP) is less understood; however, studies implicate the signal transducer and activator of transcription 1 (STAT1) pathway with IFN-γ and IL-21 noted as the predominant inflammatory cytokines." (PMID 40948686, 2025). "Of them, lichen planus, which is considered to have histological similarities with FFA, has the same keratinocyte-derived STAT1 expression pattern and it plays a role in the pathogenesis of lichen planus." (PMID 36091020, 2022).
lower respiratory tract infection (2 papers, 2020 to 2022). "Luteolin helped treat acute lower respiratory tract infection by activating STAT1 and alleviating inflammation through both inhibiting STAT3 and activating STAT6." (PMID 36324680, 2022).
malignant peripheral nerve sheath tumor (2 papers, 2020 to 2021). Malignant peripheral nerve sheath tumor (MPNST) is a rare and often aggressive soft tissue sarcoma occurring in a wide range of anatomical sites. "Similar to what was observed in ovarian cancer, malignant peripheral nerve sheath tumor (MPNST) cells are resistant to the infection of oncolytic herpes simplex virus (oHSV) through the activation of the JAK/STAT1 pathway which leads to the up regulation of ISGs." (PMID 34571790, 2021).
mesothelioma (2 papers, 2022). A usually malignant and aggressive neoplasm of the mesothelium which is often associated with exposure to asbestos. "In this case, responsive mesothelioma and renal murine tumors expressed higher amounts of inflammatory genes, downregulated IL-10RA gene expression and increased activation of signal transducer and activator of transcription 1 (STAT1)." (PMID 36672572, 2022).
mycobacteriosis (2 papers, 2022 to 2025). "As described in a systematic review, the most common manifestation in patients with STAT1 LOF mutations is Mendelian susceptibility to mycobacteriosis (MSMD), and BCG strains are the most common pathogenic agent of MSMD in patients with STAT1 LOF." (PMID 40980136, 2025). "As mutations in STAT1 and IFNGR1 are known to be responsible for both AD and AR forms of mycobacteriosis, the heterozygous variants identified in these genes (STAT1 c.373–2A>C and IFNGR1 c.40G>A/p.(Val14Met) are the most promising causal candidates in this study." (PMID 36338958, 2022).
myeloid leukemia (2 papers, 2009 to 2019). A clonal proliferation of myeloid cells and their precursors in the bone marrow, peripheral blood, and spleen. "The Stat1-nucleolin binding was additionally found in cells of the human U937 promyelocytic cell line and in the M1 mouse myeloid leukemia cells stimulated for differentiation." (PMID 20011528, 2009). "Overall, in myeloid leukemia cells, stattic not only abrogated the IFN-γ-induced STAT3 activation but also interfered with STAT1 phosphorylation." (PMID 31406210, 2019).
neutropenia (2 papers, 2010 to 2020). A decrease in the number of neutrophils found in the blood. "Ten patients had “undetectable” RORγt, including those with CVID (P433), periodic fever (P238), STAT1 (P54), WAS (P154), chronic muco-cutaneous candidiasis (P379), two with neutropenia (P63 and P66), and three with SCID (P140, P394, and P365)." (PMID 32670274, 2020). "Notably, FOXP3 was undetectable in one patient (CVID), RORγt was undetectable in six patients (one CVID, one CID, two neutropenia, one WAS, and one CMC), and both were undetectable in four patients (two SCID, one STAT1, and one periodic fever)." (PMID 32670274, 2020).
Oral leukoplakia (2 papers, 2015 to 2025). A thickened white patch on the oral mucosa that cannot be rubbed off. "STAT1+ cells were widely distributed in the subepithelial lesions of leukoplakia." (PMID 26242181, 2015). "To further characterize the CD163+ macrophages in leukoplakia, we examined the coexpression of CD163 and STAT1 or pSTAT1 using double-labeling immunofluorescence." (PMID 26242181, 2015). "Because Th1 cells produce IFN, which induces M1 macrophages, we next assessed whether the IFN-inducible gene products STAT1 and CXCL9/Mig, a chemokine for Th1, were expressed in leukoplakia." (PMID 26242181, 2015).
ovarian tumor (2 papers, 2020 to 2021). "It has been demonstrated that integrin β 1 (ITGB1), which is upregulated in OC, promotes ovarian tumor growth and progression and inhibits apoptosis by upregulating STAT1 expression." (PMID 33834023, 2021).
pancreatitis (2 papers, 2014 to 2022). Inflammation of the pancreas. "In early pancreatitis, depending on the regulation of signal transducer and activator of transcription 1 (STAT1) and STAT2 genes, IFN-α can greatly increase the expression level of PD-L1 in pancreatic islet B cells." (PMID 36704045, 2022). "However, under conditions of experimental pancreatitis, Ifnar1SA mice exhibited noticeably higher pancreatic tissue levels of IFN-stimulated proteins (STAT1 and PKR) and IFN-stimulated genes such as Irf7 compared with wild type animals." (PMID 24480543, 2014).
Papillary Thyroid Carcinoma (2 papers, 2023 to 2025). "For example, the chimeric RET/PTC (rearranged in transformation/papillary thyroid carcinoma) oncoproteins were constitutively expressed in papillary thyroid cancer and were able to phosphorylate the Tyr-107 of STAT1, which is accompanied by IRF1 expression." (PMID 37047709, 2023).
pemphigus (2 papers, 2017 to 2022). Pemphigus is a group of rare autoimmune diseases that cause blistering of the skin and mucous membranes (mouth, nose, throat, eyes, and genitals).This conditioncan occur at any age, but often strikes people in middle or older age. "By associating the co-expressed genes with GWAS results for pemphigus and SLE, IRF8 and STAT1 were characterized as the key regulatory genes." (PMID 35632621, 2022). "By associating the modular genes with genome-wide association studies (GWASs) for pemphigus and SLE, we characterized IRF8 and STAT1 as key regulatory genes." (PMID 29387060, 2017).
Peritoneal Fibrosis (2 papers, 2014 to 2023). Disorder characterized by a wide range of structural changes in PERITONEUM, resulting from fibrogenic or inflammatory processes. "Studies next tested the importance of STAT1 activation as a prerequisite to the development of peritoneal fibrosis." (PMID 24412616, 2014). "In this context, SES activates Th1 cell expansion in a IL-6Rα-dependent manner, which promotes enhanced stromal STAT1 signaling as an early prerequisite to the onset of peritoneal fibrosis." (PMID 24412616, 2014).
peritonitis (2 papers, 2017 to 2023). Inflammation of the peritoneum (tissue that lines the abdominal wall and covers most of the organs in the abdomen). "The importance of STAT1-dependent regulation of PGs was supported by using a model of zymosan-induced peritonitis in this study and likely a model of bronchial asthma in a previous study." (PMID 29255467, 2017). "The relevance of STAT1-dependent regulation of PGD2 production in vivo was supported by using a model of zymosan-induced peritonitis." (PMID 29255467, 2017). "Using a model of zymosan-induced peritonitis, the relevance of this finding in vivo was supported by marked inhibition of PGD2 and ROS produced in peritoneal exudate cells by STAT1 deficiency." (PMID 29255467, 2017). "To understand how the effector properties of Th1 cells impact the contribution of STAT1 and STAT3 in acute resolving peritonitis, we have applied next-generation sequencing methods to examine the stromal response to inflammation." (PMID 37272871, 2023). "To understand the relationship between IL-6 and IFN-γ in these processes, we tracked the activity of STAT1 and STAT3 transcription factors in stromal tissue following peritonitis." (PMID 37272871, 2023).
pneumococcal pneumonia (2 papers, 2014 to 2020). A febrile disease caused by STREPTOCOCCUS PNEUMONIAE. "Therefore, the ability of IL-27-mediated IL-17A suppression in γδ T cells to sensitize mice to secondary pneumococcal pneumonia was dependent upon STAT1." (PMID 24408967, 2014). "However, during streptococcal or pneumococcal pneumonia, AECs also express secreted and transmembrane (Sectm) 1, Sectm1a, and Sectm1b genes due to the type 1 IFN signaling induction in AECs via signal transducer and activator of transcription 1 (STAT-1) activation." (PMID 32849610, 2020).